DNMT1 (DNA methyltransferase 1)
Diseases named in the same sentence as DNMT1 in open-access papers (continued):
Sharing a sentence is not in itself a finding about the gene and the disease.
tumor (continued). "When DNMT1 was silenced or targeted with inhibitors, OSCC cells displayed quite hysteretic tumorigenic capacity and restricted tumor growth." (PMID 38755637, 2024). "MEG3 expression was negatively correlated with DNMT1 and DNMT1 knockdown increased MEG3 expression and inhibited tumor growth in mice tumor model." (PMID 38277283, 2024). "The expression levels of three writers (DNMT1, DNMT3A, DNMT3B), two erasers (TET1, TET3), and eight readers (MBD4, ZBTB33, UHRF1, UHRF2, UNG, TDG, NTHL1, SMUG1) were dramatically higher in tumor tissues (p < 0.05)." (PMID 38317133, 2024). "In DNMT1–/– cells, decitabine robustly upregulates TET2, with re-expression of tumor suppressors at 0.5 μM and 5 μM doses and aza-T-dCyd at a 0.5 μM dose only upregulates TET2 and induces p16ink4A re-expression." (PMID 39057134, 2024). "Silencing of tumor suppressors via methylation contributes to carcinogenesis, and LUCAT1 can impact this process by virtue of regulating DNA methyl transferase 1 (DNMT1)." (PMID 39594666, 2024). "This study establishes a critical role for the complex interplay between miR-152-3p, DNMT1, and SOS1 in regulating and maintaining self-renewal and tumor growth within LCSCLs." (PMID 38622665, 2024). "To delve deeper into the role of DNMT1/miR-152-3p/SOS1 expression in the self-renewal and tumor growth of NSCLCs, we conducted a comparative analysis." (PMID 38622665, 2024). "Taken together, these data provide evidence that simultaneous inhibition of DNMT1 and SMO synergistically inhibits SHH-MB tumor growth specifically by blocking SHH pathway output." (PMID 39107797, 2024). "By pharmacological inhibition of either the PRC2 component EZH2 or DNMT1, it was possible to restore the tumoral CXCR3 ligand epigenetic silencing and therefore enhance CD8+ T-cell trafficking and tumor growth control." (PMID 37046597, 2023). "At the same time, the expression levels of DNA methyltransferases (DNMT) (including DNMT1, DNMT3A and DNMT3B) in the normal and tumor samples from TCGA database were also determined." (PMID 37838802, 2023). "SHP-1 expression has an inverse relationship with DNMT1 and STAT3; its expression decreases when the activation of DNMT1 and STAT3 in tumor cells increases." (PMID 38203502, 2023). "2-Hydroxyglutarate (2-HG), a product of mutant isocitrate dehydrogenase 1 (IDH1), binds to DNA methyltransferase 1 (DNMT1) and induces the hypermethylation of the RIPK3 promoter, thereby rendering tumor cells more resistant to necroptosis." (PMID 36849530, 2023). "In addition, others have hypothesized a similar carcinogenesis model in which DNMT3A and DNMT3B are specifically recruited during tumor initiation and promotion, with a subsequent downregulation of their expression, whereas DNMT1 is involved in tumor progression." (PMID 37894317, 2023). "DNMT3A is overexpressed in the early stages only, whereas DNMT1 and DNMT3L are also overexpressed in tumor relapses." (PMID 37894317, 2023). "The E7 protein translated from the HPV16 E7 gene can bind to DNA methyltransferase 1 (DNMT1) to induce methylation of tumor suppressor genes, leading to inactivation of tumor suppressor genes and promoting tumor progression." (PMID 36741964, 2023). "knockdown of UHRF1 decreased the recruitment of DNMT1 to the CPG islands, thereby decreasing the maintenace of DNA methylation and re-elevating the epigenetic-silenced tumor suppressor genes such as RARB, CDH1, and PSP94." (PMID 36593255, 2023). "The expression of four methylated transferases (DNMT1, DNMT2, DNMT3A and DNMT3B) in various tumor types was significantly correlated with the expression of PTPN2." (PMID 37884566, 2023).
tumor (continued). "Among the differentially expressed genes present, DNMT1, NSUN2, NSUN4, and TET2 were highly expressed in LNM + tumor tissues while NSUN5 and NSUN7 expression was reduced." (PMID 37907576, 2023). "First, we considered transcript expression of DNMT1 and the cellular uptake transporter of decitabine, i.e., SLC15A1/PEPT1 in clinical samples of 275 tumor and 41 histologically proven normal resection material." (PMID 37208732, 2023). "Firstly, we began by comparing the expression of the DNMT1, DNMT3A, and DNMT3B methyltransferases in relation to MELK tumor expression, revealing that all three were up-regulated in the context of higher MELK expression." (PMID 35511171, 2022). "As epigenetic silencing decreases Th1-type chemokines to limit effector T-cell trafficking to the tumor, ICB in combination with inhibitors of EZH2 and DNMT1 slows cancer progression in ID8 ovarian cancer and CT26 colon models." (PMID 34385592, 2022). "In pre-tumor cells as well as CAC tumor cells, the increased expression of DNMT1 has been reported compared to the sporadic type." (PMID 35410210, 2022). "Immunohistochemistry confirmed the high expression of WTAP, DNMT1, and DNMT3B in tumor tissue, but the low expression of TRMT6." (PMID 36203569, 2022). "CM-272 inhibits G9a, DNMT1, DNMT3A, and DNMT3B with an IC50 of 8 nM, 382 nM, 85 nM, and 1,200 nM, respectively, and promotes the apoptosis of various tumor cells in vitro." (PMID 37077808, 2022). "More recent applications have taken advantage of its role as a DNMT1 inhibitor and used DAC to induce epigenetic changes including reactivation of methylated tumor suppressor genes and activation of antitumor immunity." (PMID 36227698, 2022). "The cytoplasmic SIRT1 colocalizes dsh protein in the cytoplasm and enhances the expression of DNA Methyl-transferase 1 (DNMT1) that promote DNA hypermethylation in the promoter domain of APC, thereby inhibiting its tumour suppressor function." (PMID 36505828, 2022). "Together, these results indicate that SETD7 has a tumour-suppressing role in BC cells possibly by inhibiting aberrant expression of E2F1 and DNMT1." (PMID 35326563, 2022). "Epigenetically, HBx also represses RIZ1, another tumour suppressor of HCC, via methytransferase 1 (DNMT1) governed hypermethylation and suppressed miR-152." (PMID 35203390, 2022). "Cooperation between PRC2 and DNMT1-mediated DNA methylation was shown to suppress the expression of T helper 1 (Th1)-type chemokines CXCL9 and CXCL10 to impede tumor infiltration of CD8+ T cells." (PMID 36323669, 2022). "Here, we showed that the novel nonnucleoside DNMT inhibitor (DNMTi) MC3343 induces a specific depletion of DNMT1 and affects EWS tumor proliferation through a mechanism that is independent on DNA methylation." (PMID 35712255, 2022). "DNMT1 suppresses tumor production of CXCL9 and CXCL10 and subsequently reduces T-cell tumor migration." (PMID 34385592, 2022). "In contrast, the expressions of NSUN3, NSUN4, NSUN7, TRDMT1, DNMT1, YBX1, and TET2 were low in tumors and had a tumor-suppressive effect." (PMID 36661693, 2022). "Further investigation illustrated that DNMT1/3A/3B, TDG, SMUG1, UNG, NEIL1, MDB3/4, ZBTB33, and UHRF1/2 were essentially upregulated in tumor samples, while TET2, MBD1, and MBD2 were downregulated in tumor samples." (PMID 35205097, 2022). "In CRC cells, linc00337 recruited DNA methyltransferase 1 (DNMT1) to the promoter region of CNN1 and restricted its transcription, promoting tumor growth and angiogenesis." (PMID 36316703, 2022). "Interestingly, while DNMT1 inhibitors can lift the repression of tumor suppressors by promoter demethylation, they can also repress oncogenes that have been activated by gene body methylation, thereby normalizing the expression of both tumor suppressors and oncogenes." (PMID 35158795, 2022). "Several genes were found at lower expression levels in tumor cases, such as AXL, BAHC2, CFLAR, and DNMT1 while others were overexpressed such as BNIP3, DIABLO, FADD, and IDH1." (PMID 35911707, 2022).
tumor (continued). "The mRNA levels of DNA methyltransferases (including DNMT1, DNMT3A, and DNMT3B) were significantly higher in KIRC patients and correlated with tumor stage and histologic tumor grade than in normal." (PMID 36186442, 2022). "In pre-clinical models, the inhibition of DNMT1 and EZH2 improves the efficacy of immune checkpoint inhibitor therapy, slows tumour progression and increases TH1-cytokine production." (PMID 35326684, 2022). "Except for NOS1, DNMT1 and CCL5, the hub genes CCL19 and CCR7 in DE-GRGs are compose of the CCL19/CCL21-CCR7 axis that exerts both immune response and tumor proliferation." (PMID 35517412, 2022). "HPV16 E7 interacts with and activates DNA-methyltransferase 1 (DNMT1), resulting in hypermethylation of anti-tumor immunity-related genes." (PMID 33800513, 2021). "HBx-downregulated miR-152 influences DNMT1 to silence both the CDH1 and GSTP1 tumor suppressors to promote carcinogenesis." (PMID 33995383, 2021). "LMP2A is also responsible for activation of DNA methyltransferase 1 (DNMT1) via STAT3 pathway, leading to the promoter methylation of PTEN tumor suppressor." (PMID 33919876, 2021). "Recently, we demonstrated the overexpression of DNMT1, DNMT3A, and DNMT3B in RMS tumour biopsies compared to normal skeletal muscle and the oncogenic role, which is played by DNMT3B in RMS." (PMID 34831178, 2021). "Increased expression of DNMT1, DNMT3A and DNMT3B has been detected in PDAC, which suggests direct involvement in the epigenetic regulation of tumor progression." (PMID 34198989, 2021). "In conclusion, we obtained several DEGs in CC and found that overexpression of DNMT1, CHAF1B, CHAF1A, MCM2, KNTC1 in tumor tissues predicted poor survival in CC." (PMID 33616161, 2021). "HDACis can also affect DNMT1 levels, a DNA methyltransferase, and abolish the activity of DNMT1 by inhibition of HDAC2, thus depleting CpG island methylation at the promoters of tumour suppressor genes." (PMID 33669182, 2021). "For instance, ROS increases the expression of Snail, a methyl-CpG binding protein that recruits DNA methyltransferase 1 (DNMT1) and histone deacetylase 1 (HDAC1), and induces the hypermethylation of E-cadherin, a tumor suppressor gene." (PMID 34679688, 2021). "Results of in vivo assay indicated that in K562 cells, versus the sh-NC group and the si-NC group, the tumor volume and weight were reduced in the sh-HOTAIR group and the si-DNMT1 group (all P < 0.05)." (PMID 33941772, 2021). "HOXA11-AS is thought to bind directly to LSD1, EZH2, WDR5, STAU1, DNMT1 and AGO2 in tumor cells, acting as a frame for EZH2 and LSD1/DNMT1 to downregulate PRSS8, KLF2 and P21 expression, thus promoting GC." (PMID 35155211, 2021). "Double-knockdown of DNMT1 and DNMT3A, showed significantly higher miR-200c (a tumor suppressor in breast cancer) expression along with increased E-cadherin and decreased vimentin expression." (PMID 33572395, 2021). "Silenced DNMT1 or upregulated miR‐152‐3p reduced TMSB10 expression and suppressed CRC progression and tumor growth." (PMID 32918845, 2020). "It has been reported that the tumor production of CXCL9 and CXCL10 was repressed by enhancement of H3K27me3 and DNMT1-mediated DNA methylation." (PMID 33031059, 2020). "Decitabine is known to degrade DNMT1, DNMT3A, and DNMT3B proteins in tumor tissue by inducing lysosomal degradation of DNMTs." (PMID 32714333, 2020).
tumor (continued). "In this work, we found that silenced DNMT1 in CRC suppressed the proliferation, migration and invasion, promoted apoptosis of cells, and decreased the tumor volume and weight in nude mice." (PMID 32918845, 2020). "We focused on DNA (cytosine-5)-methyltransferase 1 (DNMT1), a DNA-binding enzyme responsible for the down-regulation of many tumor suppressor genes through hypermethylation of their promoter regions and a downstream effector of APC/β-catenin/TCF4 signaling." (PMID 32225105, 2020). "The tumor suppressor function of miR-342-3p was mediated via inhibition of pro-survival autophagy by targeting MAP1LC3B and downregulation of DNMT1 with demethylation and re-expression of tumor suppressor genes." (PMID 33076962, 2020). "Therefore, in this context, DNMT1 may be important for tumor maintenance." (PMID 32806509, 2020). "We identify miR-484 as a metastasis specific suppressor with hypermethylation of promoter in CC and reveal a novel pathway in which DNMT1 epigenetically mediates miR-484 repression with resultant MMP14/HNF1A activation, which results in tumor metastasis in CC." (PMID 31810492, 2019). "Because PDTC reduced in vivo tumor growth in nude mice, we examined the expression of ZNF479, MT-1, ASH2L, Menin, DNMT1, and UHRF1 in PDTC-treated tumors from mice." (PMID 31138789, 2019). "By regulation of methylation via DNMT1-miRNA-148a pathway, MDE can inhibit different gene that are relatod to tumor or normal cells." (PMID 31564251, 2019). "Tumor production of the T helper 1 (Th1)-type chemokines CXCL9 and CXCL10 is epigenetically repressed by EZH2-mediated H3K27me3 and DNMT1-mediated DNA methylation in EOC." (PMID 29482595, 2018). "We detected proteins DNMT1, ICAM1 and AIF1 as being highly expressed in the outlier presumed normal tissue compared to both other controls and tumor tissue from the same patients." (PMID 30419021, 2018). "And the expression of stemness markers, OCT4 and Nanog, which were down-regulated in tumor tissues from the subcutaneous implantation models of CD133+/CD44+ cells with shOPN/EV, were partly rescued by introduction of DNMT1." (PMID 30064482, 2018). "We found that DNMT1 and DNMT3B to be consistently overexpressed in transgenic models, human tumor cell lines, as well as clinical specimens." (PMID 29100357, 2017). "Several studies have outlined the importance of DNMT1 and HDAC1 in tumor cell growth and development, hence the use of epigenetic inhibitors in the clinic." (PMID 28534825, 2017). "We also tested the effect of solamargine in tumour growth and expressions of EP4, DNMT1 and c‐Jun in xenografted mouse model." (PMID 27620163, 2017). "Chemotherapy treatments also affected the levels of DNMT1 and DNMT3A in the PFC tissues of tumor-bearing animals." (PMID 28758896, 2017). "Taken together, we propose a working model in which MYC, in addition to its role as a site-specific transcription factor, controls DNA methylation in a global manner through overexpression of DNMT1 and DNMT3B during tumor maintenance." (PMID 29100357, 2017). "In extra-CNS SCLC increased PD-1 and PD-L1 expression in SCLC tumor cells, possibly mediated via deregulation of KIT and DNA methyltransferase 1 (DNMT1), correlated with cisplatin resistance." (PMID 29050358, 2017). "Caga increases the phosphorylation of protein kinase B (Akt), leading to activation of NFkB, up-regulation of DNA-(cytosine-5)-methyltransferase-1 (DNMT1) and tumour suppressor hypermethylation." (PMID 28238104, 2017). "miR-200b had been found to suppressed cell EMT process and functioned as a target of EZH2, such as, DNMT1 and EZH2 mediated methylation silences the microRNA-200b/a/429 gene and promotes tumor progression." (PMID 28615992, 2017).
tumor (continued). "Consistent with findings in GBM tumour tissues, NF2 and DNMT1 levels were decreased and increased, respectively, in these cells." (PMID 28764788, 2017). "In the current study, we report silencing DNMT1 inhibits proliferation, metastasis and invasion in ESCC cells, and suppresses tumor growth of ESCC in nude mice." (PMID 27286455, 2016). "Introduction of latent membrane protein 1 (LMP1), a viral oncoprotein from EBV, into a breast cancer cell line (MCF-7) activated DNMT1, DNMT3A, and DNMT3B, and induced methylation-silencing of tumor-suppressor gene CDH1." (PMID 26823082, 2016). "Here we demonstrate in several tumor cell lines an interaction between KDM1A and both DNMT1 and DNMT3B." (PMID 27449289, 2016). "Although this work reveal the potential of DNMT1 as therapeutic target of ESCC, further investigation is needed to unveil the mystery about utilizing DNMT1 to develop tumor-oriented reagent for WSCC therapy." (PMID 27286455, 2016). "The possible mechanisms corresponding to these effects are proposed to involve tumor suppressor induction and DNA DSB repair repression orchestrated by DNMT1 inhibition, respectively." (PMID 27525019, 2016). "The expression levels of both DNMTs were increased in tumor samples: median RQ value for DNMT3B was 3.81 and for DNMT1 1.38." (PMID 26112163, 2015). "It has been confirmed in studies showing that DNMT1 interact physically with HDAC1 or 2, and that DNMTs recruit class I HDACs to function as co-repressors in the transcription of tumour suppressor genes." (PMID 26703571, 2015). "Relatively higher expression of DNA methyl-transferases (DNMT1 and DNMT3b) and HIF-1α genes (34-50%, P<0.05) were also detected in tumor tissues." (PMID 25938433, 2015). "In summary, here we demonstrate that curcumin down-regulates DNMT1 expression, which results in DNA hypomethylation and reactivation of TSGs in AML, and also correlates to its role as an inhibitor of tumor growth, both in vitro and in vivo." (PMID 23457487, 2013). "In vitro studies using non-colonic cell lines have indicated that miR-148a exerts a tumor suppressive function by targeting several genes such as PXR, TGIF2, MSX1, CDC25B, DNMT1 and DNMT3b." (PMID 23056401, 2012). "By using two different cell types, primary human fibroblasts (IMR90) and stable near-diploid tumor cells (HCT116), we determined that DNMT1 transient depletion had different outcomes related to the genetic context of the cell." (PMID 22305267, 2012). "In IMR90 cells DNMT1 depletion resulted primarily in cell cycle arrest, while in HCT116 tumor cells, missing p14ARF, induced aneuploidy, probably affecting the correct chromosomal segregation by altering the DNA methylation pattern." (PMID 22305267, 2012). "MeDIP-qPCR and qPCR were performed to measure demethylation status and mRNA re-expression level of 7 tumor-suppressor genes (CCNA1, CHFR, FHIT, PAX1, PTEN, SFRP4, TSLC1) in Hela and Siha cells after silencing DNMT1." (PMID 21999220, 2011). "We selected 5 known tumor-related genes i.e., K-ras, c-MYC, DNMT1, Tpd52, CDKN1b for PCR confirmation." (PMID 22206623, 2011). "DNMT1 has been shown to competitively bind to proliferating nuclear cell antigen (PCNA) at the same site as p21, a tumor suppressor that inhibits DNA replication." (PMID 22303414, 2011). "P-LISA and ELISA experiments realized from non-tumor and tumor breast cell lines revealed that that tumor cells (MDA-MD-231 and Cal-51) harbored less Dnmt1/PCNA interactions and less 5-methycytosine (5 mC) than non-tumor cells (MCF10A)." (PMID 21470401, 2011). "In parallel with these results, we noted that the phosphorylation levels of Dnmt1, at residues preferentially recognized and phosphorylated by Akt and PKC (pDnmt1-PAS and pDnmt1-PPCS, respectively), increased when the tumor grade increased." (PMID 20613874, 2010). "Studies on the depletion of DNMT1 and DNMT3B in tumour cells have implied that they play an important role in tumour development." (PMID 20128888, 2010).